ROCK1P1 (Rho associated coiled-coil containing protein kinase 1 pseudogene 1 )
Synonyms: ROCK1P
Gene: Long non-coding RNA gene on chromosome 18 (95,663 to 141,973, forward strand). Ensembl gene ENSG00000290877.
Diseases named in the same sentence as ROCK1P1 in open-access papers:
ROCK1P1 is named in the same sentence as 3 diseases in open-access papers, as found by Europe PMC text mining. Sharing a sentence is not in itself a finding about the gene and the disease.
ROCK1P1 shares sentences with these, for which no sentence is quoted: mood disorder (1 paper); schizophrenia (1); tumor (1).